IMMP2L (inner mitochondrial membrane peptidase subunit 2)
Description:
Catalyzes the removal of transit peptides required for the targeting of proteins from the mitochondrial matrix, across the inner membrane, into the inter-membrane space. Known to process the nuclear encoded protein DIABLO.
Synonyms: IMP2; IMMP2L-IT1; IMP2-LIKE
Tractability: Antibody: UniProt predicts a signal peptide or a membrane-spanning region. PROTAC: ubiquitination databases record sites on it.
Gene: Protein-coding gene on chromosome 7 (110,662,644 to 111,562,517, reverse strand). Ensembl gene ENSG00000184903.
Subcellular location: Mitochondrion inner membrane
Subcellular location (Human Protein Atlas): Mitochondria; End piece; Flagellar centriole; Principal piece
Gene Ontology:
Molecular function: endopeptidase activity; peptidase activity; serine-type endopeptidase activity; serine-type peptidase activity; signal peptidase activity
Biological process: protein localization to mitochondrion; protein processing; proteolysis
Cellular component: mitochondrion; mitochondrial inner membrane; mitochondrial inner membrane peptidase complex; membrane
Genetic constraint (gnomAD): Loss-of-function variants: 5 observed, 5.36 expected, observed/expected ratio (o/e) 0.93, 90% interval 0.48 to 1.76. That is too few expected variants to judge how well the gene tolerates losing a copy. Missense variants: 65 observed, 58.31 expected, observed/expected ratio (o/e) 1.11, 90% interval 0.91 to 1.37. Synonymous variants: 17 observed, 20.83 expected, observed/expected ratio (o/e) 0.82, 90% interval 0.56 to 1.22.
Homologues: Orthologues: macaque IMMP2L (100% identical), chimpanzee IMMP2L (99% identical), pig IMMP2L (97% identical), guinea pig IMMP2L (93% identical), mouse Immp2l (91% identical), rat Immp2l (91% identical), tropical clawed frog immp2l (78% identical), zebrafish immp2l (69% identical), Drosophila melanogaster CG11110 (54% identical), Caenorhabditis elegans immp-2 (37% identical). Paralogues in human: IMMP1L (29% identical).
Diseases named in the same sentence as IMMP2L in open-access papers:
IMMP2L is named in the same sentence as 37 diseases in open-access papers, as found by Europe PMC text mining. Sharing a sentence is not in itself a finding about the gene and the disease. The quoted sentences say what the papers report.
autism (17 papers, 2011 to 2024). Persistent deficits in social interaction and communication and interaction as well as a markedly restricted repertoire of activity and interest as well as repetitive patterns of behavior. "In this respect, GPD2 has been deleted and mutated in autism, and IMMP2L is strongly linked with autism inheritance; however, the molecular basis of these associations has yet to be established." (PMID 38256063, 2024). "Mitochondrial dysfunction is strongly associated with autism spectrum disorder (ASD) and the Inner mitochondrial membrane protein 2-like (IMMP2L) gene is linked to autism inheritance." (PMID 37761857, 2023). "One such risk gene is IMMP2L which is located at the 7q31 chromosome locus that has been repeatedly linked with autism inheritance." (PMID 37761857, 2023). "Behavior changed in the Immp2l knockdown or knockout mice, which is linked with autism." (PMID 39456903, 2024). "Notwithstanding, autism is strongly associated with mitochondrial dysfunction and IMMP2L encodes a key peptidase localized within the inner mitochondrial membrane that processes other mitochondrial proteins through the removal/cleavage of mitochondrial-specific signal peptides." (PMID 37761857, 2023). "However, mutations in other autism risk genes, such as immp2l and adra1aa, also lead to fish that exhibit tighter shoaling, indicating a convergent social phenotype, at least for a subset of zebrafish ASD models." (PMID 36613611, 2022). "IMMP2L has previously been investigated in relation to ovarian aging and autism; however, limited research has been conducted on its association with KOA." (PMID 39259428, 2024). "Another family-based association study focused on zinc finger protein 533 (ZNF533), DOCK4, and IMMP2L genes in the Chinese Han population showed that SNPs within ZNF533 and DOCK4 were related to autism, whereas IMMP2L was shown irrelevant." (PMID 32244359, 2020). "One of the suggested GTS susceptibility genes is the inner mitochondrial membrane peptidase, subunit 2 (IMMP2L), and structural variants involving this gene are also implicated in other neurobiological/neuropsychiatric conditions including autism and ADHD." (PMID 32265818, 2020). "Genes that have long been mentioned as involved in the causation of autism are FOXP2, RAY1/ST7, IMMP2L, and RELN genes at 7q22-q33." (PMID 32244359, 2020). "TOP2B2 peaks from untreated cells are associated with three genes (CNTN4, IMMP2L and SATB2) implicated in both autism and schizophrenia whilst TOP2B2 peaks from E2-treated cells are associated with five genes (CNTN4, IMMP2L, EPC, SMG6 and CACNA1C)." (PMID 26459242, 2015). "Regulation of expression of both AUTS2 and IMMP2L by wig-1 suggests a possible role for wig-1 in autism." (PMID 22347364, 2012). "IMMP2L was another target gene of Tourette’s syndrome and autism." (PMID 36980855, 2023). "Our analysis supports the role of several genes/loci associated with autism (e.g., NRXN1, ADNP, 22q11 deletion) and identified new truncating (e.g., GRIK2, ROBO1, NINL, and IMMP2L) or recessive deleterious variants (e.g., KIRREL3 and CNTNAP2) affecting autism-associated genes." (PMID 30675382, 2019). "Deletions involving IMMP2L have been associated with ADHD, autism, and Tourette syndrome." (PMID 22102821, 2011). "Many of these CNVs encompass genes included in the best‐known lists of candidate genes for autism, including CTNNA3 (OMIM #607667), MACROD2 (OMIM #611567), IMMP2L (OMIM #605977), PARK2 (OMIM #600116), LZTS2 (OMIM #610454), and LRP1 (OMIM #107770)." (PMID 37186221, 2023).
Tourette syndrome (16 papers, 2011 to 2025). A neurologic disorder caused by defective metabolism of the neurotransmitters in the brain. "Defects in the human homologue IMMP2L are associated with a wide spectrum of neurodevelopmental disorders, including Tourette syndrome." (PMID 37859837, 2023). "The IMMP2L gene (inner mitochondrial membrane peptidase subunit 2) is implicated in Gilles de la Tourette syndrome (GTS, OMIM 137580), Alzheimer’s disease, autism spectrum disorder (ASD), schizophrenia, and other neurodevelopmental disorders." (PMID 36553064, 2022). "Variants in IMMP2L have been associated with a small subset of patients with Tourette syndrome with dominant inheritance." (PMID 33426505, 2020). "Mutations in IMMP2L have been linked to Alzheimer’s disease, ID, and Tourette’s syndrome." (PMID 39533101, 2025). "Interestingly, the IMMP2L locus has been linked with Autism Spectrum Disorders (ASDs) and with Tourette Syndrome." (PMID 22347364, 2012). "In a Danish cohort study investigating CNVs in 188 unrelated patients with Tourette syndrome, seven patients were found to have IMMP2L deletions, which were also restricted to exons 1–3." (PMID 35776734, 2022). "Of note, IMMP2L encodes the second subunit of the inner mitochondrial membrane peptidase complex and has previously been reported as a potential candidate gene associated with ASD, Tourette syndrome and other NDDs." (PMID 33407644, 2021). "In conclusion, we identified a positive association between rs1042201 in AADAC gene and a significant association between rs3750486 in the LHX6 and rs7795011 in the IMMP2L genes with Tourette Syndrome, thus providing support for their possible biological role in the etiology of the disorder." (PMID 32922348, 2020). "IMMP2L gene has been indicated as a possible candidate for Gilles de la Tourette syndrome." (PMID 25478008, 2014). "Recently, genome-wide linkage studies have identified genomic imbalances involving IMMP2L gene in 7q31.1 that are associated with autistim spectrum disorders (AUTS9) (MIM 611015), attention deficit/hyperactivity disorder (ADHD) (MIM 143465) and Gilles de la Tourette syndrome (GTS) (MIM 137580)." (PMID 25478008, 2014). "A number of smaller studies had suggested that IMMP2L may be deleted at higher frequencies in ASD, Gillies de la Tourette syndrome (GTS), attention deficit hyperactivity disorder, (ADHD) and intellectual disability (ID) populations." (PMID 37761857, 2023).
autism spectrum disorder (8 papers, 2012 to 2024). A spectrum of developmental disorders that includes autism, and Asperger syndrome. "In line with this, rare structural variants affecting IMMP2L were implicated as susceptibility factors in autism spectrum disorders and ADHD." (PMID 32265818, 2020). "Interestingly, deletions in IMMP2L have been previously linked with autism spectrum disorder." (PMID 35776734, 2022). "For example, constitutional intragenic deletions within AUTS2, IMMP2L, and NRXN1 have been associated with autism spectrum disorder, intellectual disability, and psychiatric disorders." (PMID 25373142, 2015).
Infertility (6 papers, 2013 to 2024). "We previously reported that Immp2l mutation in mice causes excessive mitochondrial superoxide generation, which causes infertility and early signs of aging." (PMID 24251118, 2013). "Immp2l plays an important role in maintaining ovarian function, and the deficiency of the Immp2l gene in mice causes infertility due to ovarian aging, which is caused by the cessation of ovarian follicle development in the secondary stage, as well as ovulation disorder." (PMID 39456903, 2024). "When the inner mitochondrial membrane peptidase 2-like encoded by Immp2l was ablated, the resulting mutant females were deficient in folliculogenesis and ovulation and infertile, probably because of low availability of nitric oxide caused by mitochondrial dysfunction." (PMID 35600599, 2022). "Some studies have already demonstrated that mitochondrial superoxide level was increased in Immp2l mutant mice, which lead to spermatogenic damage and infertility." (PMID 35095490, 2021). "These evidences suggest that oxidative stress is an important mediator of infertility and Immp2l-/- mice act as one of the ideal animal models of infertility, alleviating oxidative stress is conducive to ameliorating spermatogenesis of Immp2l mutant mice." (PMID 35095490, 2021). "Immp2l knockout mice exhibit mitochondrial dysfunction, increased ischemic brain damage, and infertility.The human IMMP2L mRNAs are ubiquitously expressed in various tissues except for adult liver and lungs." (PMID 26903887, 2016).
Alzheimer disease (3 papers, 2018 to 2025). A progressive, neurodegenerative disease characterized by loss of function and death of nerve cells in several areas of the brain leading to loss of cognitive function such as memory and language. "The history of Alzheimer’s disease in the carrier mother is interesting, particularly because the IMMP2L gene encodes a mitochondrial protein that regulates the levels of reactive oxygen species, and has been implicated in Alzheimer’s disease susceptibility." (PMID 29882083, 2018).
Ataxia (3 papers, 2013 to 2023). Ataxia refers to impaired coordination of voluntary muscle movement. "We recently showed that mice with a mutation in the Inner Mitochondrial Membrane Peptidase 2‐like (Immp2l) gene had elevated levels of mitochondrial superoxide, impaired fertility and age‐associated phenotypes, including kyphosis and ataxia." (PMID 26616244, 2016). "This contrasts with the earlier truncated Immp2lTg(Tyr)979Ove mouse that suggested loss of Immp2l activity was associated with an increase in ROS production and oxidative stress phenotypes including oxidative stress in the brain causing ataxia and neurodegeneration." (PMID 37761857, 2023). "Following our observation of ataxia in Immp2l−/− mice older than 16 months, this manuscript reports age‐dependent CGN degeneration in old Immp2l−/− mice, and the protective effects of the antioxidant SkQ1 on CGN degeneration." (PMID 26616244, 2016). "Previously we reported that Immp2l−/− (written as −/− thereafter) mice develop progressive ataxia starting from the age of 16 months." (PMID 26616244, 2016). "Normal control mice and Immp2l+/− mice do not develop ataxia at the age of up to 30 months, the oldest age examined." (PMID 26616244, 2016). "Although their lifespans are not reduced compared to normal control mice, Immp2l−/− mice show erectile dysfunction, defective oogenesis, reduced food intake, bladder dysfunction, early onset of ataxia and kyphosis, and age‐dependent spermatogenic damage." (PMID 26616244, 2016). "Furthermore, age-related defects such as ataxia in Immp2l mutant mice may not be secondary to reduction in food intake either." (PMID 24251118, 2013).
thyroid cancer (3 papers, 2017 to 2022). "In breast and thyroid cancer, genes corresponding to the intersection sites (rs11191419, rs13240464, rs7432375) included SFXN2, AS3MT, IMMP2L, and PCCB." (PMID 36138824, 2022). "Interestingly, there is relative lack of knowledge on the role of the remaining three genes, i.e. IMMP2L, RARRES1 and CARD9-SNAPC4 in thyroid cancer." (PMID 35976137, 2022).
dyslexia (2 papers, 2014 to 2016). A learning disorder characterized by an impairment in processing written words. "Tracing chromosomal aberrations in TS patients, IMMP2L has also been implicated in TS and other neurodevelopmental disorders, such as ASD, ADHD and dyslexia; yet IMMP2L coding mutations have not been identified." (PMID 27536211, 2016).
Intellectual disability (2 papers, 2015 to 2023). "Moreover, differential DNA methylation of IMMP2L in families with maternally inherited 7q31.1 deletions has been shown to be associated with intellectual disability and developmental delay." (PMID 38161384, 2023).
keratoconus (2 papers, 2017 to 2018). A degenerative, structural disorder of the eye, characterized by a cone-shaped protrusion of the cornea. "We also found association of keratoconus with IMMP2L, a mitochondrial inner membrane protease." (PMID 28676647, 2017). "We identified 8 SNPs in 6 genes/loci that were associated with keratoconus, i.e., FOXO1 rs2721051, FNDC3B rs4894535 and BANP-ZNF469 rs9938149 for the overall combined cohorts, and RXRA-COL5A1 rs1536482, IMMP2L rs757219 and rs214884, and COL4A4 rs2229813 and rs2228557 for Whites." (PMID 28676647, 2017). "In conclusion, we have prioritized 8 SNPs in 6 genes/loci as significant genetic markers for keratoconus in Whites, including FOXO1 rs2721051, RXRA-COL5A1 rs1536482, FNDC3B rs4894535, IMMP2L rs757219 and rs214884, and BANP-ZNF469 rs9938149, and COL4A4 rs2229813 and rs2228557." (PMID 28676647, 2017).
Obesity (2 papers, 2013 to 2024). Accumulation of substantial excess body fat. "Global deletion of Hdac9 protects against high-fat diet (HFD) induced obesity and metabolic disease in mice, and Immp2l is associated with food intake." (PMID 38483771, 2024). "Our data indicate that Immp2l mutation has little effect on the food intake and obesity of ob/ob mice." (PMID 24251118, 2013). "We mutated Immp2l gene in ob/ob mice and found that it had little effect on the food intake and obesity of ob/ob mice." (PMID 24251118, 2013).
age (1 paper, 2016). A temporal measurement of the time period elapsed since an identifiable point in the life cycle of an organism. "Copy number variations and SNVs have been reported to alter the inner mitochondrial membrane peptidase subunit 2 encoded by IMMP2L, causing neurodevelopmental disorders and age-associated neurodegeneration, respectively." (PMID 27799064, 2016).
attention deficit-hyperactivity disorder (1 paper, 2010). A disorder characterized by a marked pattern of inattention and/or hyperactivity-impulsivity that is inconsistent with developmental level and clearly interferes with functioning in at least two settings (e.g. at home and at school). "In contrast to recent CNV studies on attention-deficit/hyperactivity disorder, our data therefore suggest that haploinsufficiency of IMMP2L might be benign, with deletions of DOCK4 more likely to be of etiological relevance." (PMID 20346443, 2010).
breast carcinoma (1 paper, 2016). "Numerous studies reported that IMMP2L may act as risk factor for neurological disease and it has been associated with breast cancer, although its role is not clear." (PMID 27895661, 2016).
Fanconi anaemia (1 paper, 2021). "Among these, there were FHIT, WWOX, FANCC (belonging to the Fanconi anaemia pathway), CADM1, and IMMP2L." (PMID 34187875, 2021).
language disorder (1 paper, 2018). A category of disorders characterized by an impairment in the development of an individual's language capabilities, which is in contrast to his/her non-verbal intellect. "The 7q31 deletion was considered a risk factor in several neuropsychiatric disorders, including ASD, ADHD and language disorder and partial deletions of the IMMP2L gene in particular has been described as risk factors for neurological diseases with an incomplete penetrance." (PMID 29882083, 2018).
liver cancer (1 paper, 2024). An epithelial or non-epithelial malignant neoplasm that arises from the liver. "Among these, six genes were significantly differentially expressed between liver cancer tissue and adjacent normal tissue (CSAD, SLC16A11, LILRA2, IMMP2L, GLP2R, and DHDH)." (PMID 38927691, 2024).
obsessive-compulsive disorder (1 paper, 2022). A disorder characterized by the presence of persistent and recurrent irrational thoughts (obsessions), resulting in marked anxiety and repetitive excessive behaviors (compulsions) as a way to try to decrease that anxiety. "Patients harboring the 7q31.1 deletion, which includes IMMP2L, have been reported to present some repetitive behavioral phenotypes and/or obsessive-compulsive symptoms observed in ASD, obsessive-compulsive disorder, and GTS." (PMID 35776734, 2022).
oligospermia (1 paper, 2021). Decreased number of spermatozoa in the semen. "While compared with normal mice, all untreated Immp2l mutant mice showed impaired spermatogenesis, disorganized and vacuolated seminiferous tubules, consistent with oligospermia." (PMID 35095490, 2021). "Thus, we employed the Immp2l mutant mice to investigate the protective effects of Guilingji on oligospermia induced by oxidative stress." (PMID 35095490, 2021).
prostate carcinoma (1 paper, 2020). A carcinoma that arises from epithelial cells of the prostate gland. "In agreement with these publications, our experiments showed that mGPDH had only one cleavage site and that it was after Ala42 most probably by IMMP2L peptidase that we also found significantly increased in the prostate cancer LNCaP cell line." (PMID 32717855, 2020). "The level of IMMP2L protein was significantly increased in the prostate cancer cell line." (PMID 32717855, 2020).
psychosis (1 paper, 2022). "For example, in addition to psychosis, the three patients harboring a deletion in IMMP2L exons 2 and 3 had autistic features." (PMID 35776734, 2022). "In this study, PEN-SCZ patients I and II, who carried deletions in IMMP2L exons 1–3, presented with additional autistic features, including limited social communication skills in addition to psychosis." (PMID 35776734, 2022).
transient cerebral ischemia (1 paper, 2024). "Mutations in IMMP2L can increase the risk of cerebral injury induced by transient cerebral ischemia, inhibit and decrease cellular activity, promote ROS generation, and reduce mitochondrial membrane potential." (PMID 38575125, 2024).